AFP (alpha fetoprotein)
Diseases named in the same sentence as AFP in open-access papers (continued):
Sharing a sentence is not in itself a finding about the gene and the disease.
tumor (continued). "Baseline PIVKA-II and AFP levels increased significantly with tumour stage." (PMID 34853657, 2021). "The variables age, time on the waiting list, AFP level before LTx, Milan status at listing (based on imaging), and tumour progression were included in a multivariable Cox regression analysis to determine their influence on DFS and OS in the bridging therapy subgroup." (PMID 33839747, 2021). "In addition, positive RECK expression was associated with a lower incidence of vascular invasion and recurrence, a lower level of alpha fetoprotein (AFP) and microvessel density and a better tumor differentiation." (PMID 34093791, 2021). "Regarding clinical factors, we found that tumor size, but not AFP, was significantly associated with the initial treatment response, which was consistent with a previous study." (PMID 34745952, 2021). "The eligibility criteria can consider many factors besides the tumor size and number, such as tumor biology (including alpha-fetoprotein [AFP] level), transplant benefit (i.e., the likelihood of survival on the waitlist and after LT), availability of donor organs, and composition of the waitlist." (PMID 34638395, 2021). "A recent study confirmed the power of AFP for prediction of tumor recurrence and found that the AFP could improve the performance of the Milan criteria." (PMID 34065172, 2021). "The tumour markers alpha-fetoprotein and carcinoembryonic antigen were also within normal limits." (PMID 34589351, 2021). "Therefore, factors related to tumor burden, tumor size, tumor number, mPVTT extension, and AFP, which were varied in a relatively large range, shown major roles in Cox regression analysis." (PMID 34513667, 2021). "Serum GGT levels and especially combination serum GGT plus albumin levels, were significantly associated both with HCC patient survival and tumor aggressiveness characteristics, regardless of AFP levels in a large Turkish cohort." (PMID 34540270, 2021). "Indeed, serum MCP-1 was reported to be positively correlated with α-fetoprotein (AFP) levels, suggesting it as another tumor marker in HCC." (PMID 34921636, 2021). "Currently, serum AFP is the most widely used tumor marker for the detection and monitoring of HCC." (PMID 32330203, 2020). "In addition, the YAP-induced HCC mice model showed significant tumor occurrence inhibition, suppressing the tumor markers of AFP and DCP when DTA was administered within the first 4 months after the initiation of oncogene." (PMID 32085552, 2020). "Additionally, the guiding effects of tumor size, AFP, CEA, CGA, and albumin on prognosis were limited." (PMID 32590784, 2020). "The serum AFP value in this study was obtained by a blood test, which represented the property of the whole tumor in three dimensions, while AEF was obtained only from a transverse section of the tumor in limited single dimension, whose heterogeneity would, on the contrary, be enlarged cubically." (PMID 32850426, 2020). "Indeed, the predictive factors used in this study, such as tumor diameter, tumor number, AFP, PIVKA-II, and portal vein invasion, were well-identified parameters in previous studies." (PMID 33003306, 2020). "To verify the performance of the optimal DNN model, we created several additional DNN models by including factors according to two aspects of tumor burden: imaging-based tumor burden (maximum tumor diameter, tumor number, and portal vein invasion) and biochemical tumor burden (AFP and PIVKA-II)." (PMID 33003306, 2020). "In the univariate analysis, variables associated with cancer-related death were age (HR: 1.029, p = 0.003), fibrosis grade (HR: 1.209, p = 0.015), pre-operative serum AFP level (HR: 1.308, p = 0.026), tumor stage (HR: 1.854, p = 0.003) and pre-operative serum WFA+-M2BP level (HR: 3.178, p < 0.001)." (PMID 32221384, 2020). "Thus, the purpose of this study was to investigate the molecular mechanism through which AFP promotes tumour cell proliferation by interfering with the RA‐RAR signal pathway." (PMID 33090723, 2020).
tumor (continued). "Elevated preoperative GGT levels are associated with an unfavorable tumor burden and serve as an independent prognostic marker for worse outcomes in AFP-negative HCC patients following resection." (PMID 32695241, 2020). "Consistently, a strong alpha fetoprotein (AFP) signal was detected in the tumor tissue." (PMID 32296582, 2020). "Even in the six HCC patients with elevated AFP levels, Trim22 mRNA analysis revealed decreased expression in the tumor compared to the background non-tumor in five of the six patients (83.3%) and most of these patients (4/5) had Trim22 mRNA levels less than 0.5." (PMID 31979338, 2020). "Therefore, several centers have developed criteria that include tumor biological indices such as alpha‐fetoprotein (AFP) or des‐gamma‐carboxy prothrombin (DCP) indices to predict outcomes." (PMID 32724885, 2020). "Moreover, Zhang and Yang's study indicated that AFP level rarely rose when HCC tumor mass was less than 2 cm in diameter." (PMID 33062075, 2020). "Multivariate analysis showed that upregulated UBE2M expression could be a significant factor for predicting poor survival (P < 0.01) when UBE2M expression level, TNM stage, AFP, tumor size, and tumor differentiation were included based on univariate analysis." (PMID 32012120, 2020). "However, TACE + RFA and TACE alone showed similar effects in patients with AFP ≥400 ng/ml, tumor number ≥3, tumor diameter ≥5 cm, HVTT, or PVTT + HVTT." (PMID 32884569, 2020). "Gastric hepatoid adenocarcinoma is considered a more aggressive tumor than AFP-GC." (PMID 32093729, 2020). "Vascular invasion, both micro- and macroscopic, is considered the strongest predictor of HCC recurrence, although other variables, such as tumor size, number of nodules, AFP level, degree of differentiation, and satellite nodules have also been associated with recurrence." (PMID 31940413, 2020). "Tumor response on imaging was also correlated with oncomiRs and serial changes in serum AFP." (PMID 33614488, 2020). "Alpha-fetoprotein (AFP) is the most widely available tumor biomarker used in the detection of HCC." (PMID 32021853, 2020). "In addition, AFP and NSE levels were also statistical associated with PFS except in the following variables, i.e., Age > 60, Smoking status, Differentiation status, Tumor status, Therapy (3-drugs), and Curative response (disease progression)." (PMID 32582542, 2020). "In addition, AFP expression was analysed on paraffin-embedded tumour material at the end of treatment." (PMID 33144587, 2020). "Statistical analyses revealed that the following preoperative prognostic factors were independently significant (p < 0.05) in the left-sided group: indocyanine green retention rate at 15 min, alpha fetoprotein, protein induced by vitamin K absence or antagonists-II level, and larger tumor size." (PMID 33272298, 2020). "Elevations of β-HCG and AFP confirm a malignant component to the tumor." (PMID 33005196, 2020). "The AFP model combined AFP level with tumor size and number." (PMID 32974380, 2020). "The difference in sex, tumor volume, and AFP level were statistically significant (P < 0.05)." (PMID 33330062, 2020). "Previous studies suggested that tumor response may be detected earlier by changes in AFP than by imaging studies, and changes in AFP are strong prognostic factors for survival outcomes with better consistency than radiologic response-based criteria." (PMID 33277619, 2020). "Elevated AFP is present in 95–98% of the cases, with it being used as a tumoural marker for its diagnosis and follow-up to check for regression or recurrence of the tumour." (PMID 32462465, 2020). "Cox regression revealed that a tumour number equal or greater to two (HR 1.54), AFP > 400 μg/l (HR 1.14), serum albumin < 3.6 g/dl (HR 1.63) and total bilirubin > 0.9 mg/dl (HR 1.58) were independent risk factors in our population, excluding patients with subsequent LTX." (PMID 32125515, 2020).
tumor (continued). "Prediction of tumor response to differentiate CR+PR from PD, group 1 using serum AFP ratio alone in ROC curve of AFP producer group (n = 45) had shown AUC 0.833 (95% CI, 0.69–0.98) at a cut off 1.23 with 80.0% (95% CI, 51.9–95.7) sensitivity and 88.5% (95% CI, 69.9–97.6) specificity." (PMID 33614488, 2020). "In this work, we have examined two DNA aptamers derived against the tumor biomarker AFP." (PMID 32365872, 2020). "We found that AFP 464 increased splenic cytotoxic activity, diminished the number of systemic and local Treg lymphocytes and MDSCs as well as and induced a M1 phenotype in peritoneal macrophages of M05 tumor-bearing mice." (PMID 32443455, 2020). "In addition, patients characterized as male and single and having AFP > 15 ng/mL, tumor size ≤3 cm, multiple tumors, and stage III of the 6th AJCC stage were likely to have high-Fb scores." (PMID 32539768, 2020). "Additionally, HBsAg, AFP, tumor size, and resection type were identified as insignificant independent prognostic factors in the validation dataset." (PMID 32140448, 2020). "Progressive disease was defined based on an increased tumor size and AFP of more than 25%." (PMID 33142892, 2020). "Additionally, high expression of SNRPB was positively correlated with tumor size (P = 0.001), adjacent organ invasion (P = 0.003) and serum AFP level (P = 0.004)." (PMID 33289700, 2020). "If there are two typical imaging findings and alpha‐fetoprotein elevation, biopsy should be avoided, and when the tumor is under the liver capsule, when punctured, we should do our best to pass the normal liver parenchyma and ablate the needle in the process of needle withdrawal." (PMID 32702175, 2020). "Consequently, some transplantation centers include tumor markers in their patient evaluations, such as AFP and DCP, the levels of which are correlated with HCC recurrence rate." (PMID 32466780, 2020). "It is frequently measured in clinical practice during the course of HCC treatment based on the hypothesis that AFP is continuously reflective of tumor activity and burden." (PMID 33614488, 2020). "Interestingly, all of these three scores are composed by the same three variables, namely AFP, tumor number, and diameter." (PMID 32075133, 2020). "The C-index of the nomogram for RFS was 0.649, which was statistically higher than the PLR (0.549), AFP (0.564), tumor encapsulation (0.561), tumor diameter (0.582), HBV-DNA (0.542), tumor number (0.538), ishak inflammation score (0.567) and MVI (0.559) (all P < 0.001)." (PMID 33178607, 2020). "In addition, we also demonstrated that the contents of SEPCs were related to the expression of AFP, tumour size, and differentiation grade of HCC." (PMID 33312206, 2020). "In our series, 13 of 18 patients were not eligible for complete resection at any stage of therapy before, but at HDCT, only 5 of 18 patients showed elevated AFP and 4 patients showed viable tumor cells in the tumor resected during or after standard dose chemotherapy." (PMID 33352733, 2020). "However, in their study, most HCC patients had an elevated serum AFP level, large tumor size, daughter nodules, and more advanced stage tumor than our study patients." (PMID 31979338, 2020). "In addition to the BCLC staging, AFP level which is a tumor marker helps in the diagnosis of HCC as well as provide insights into the treatment pattern." (PMID 32339207, 2020). "C-reactive protein (CRP) and Platelet lymphocyte ratio (PLR) could be considered as tumor markers for low-AFP HCC patients, and possess parameter values for tumor growth and invasiveness." (PMID 32518728, 2020). "Tumor marker like AFP or PIVKA-II would be indicators for the effectiveness of the drug." (PMID 33301055, 2020). "In this situation, the combination of AFP with other tumor markers might improve the predictive ability of tumor recurrence and survival." (PMID 32850396, 2020).
tumor (continued). "Therefore, it is plausible that the patient had significant circulating tumor cells at the time of sample collection since his AFP was also significantly elevated." (PMID 32741373, 2020). "This tumor showed positivity for AFP, GLP3 and SALL4, and negativity for CK7 and EMA." (PMID 32493368, 2020). "Furthermore, ARID1A-low subtype remained as significant predictor when AFP level and tumor size were included in multivariate analysis (HR 1.413, CI 1.234-1.619, p < 0.01)." (PMID 32878261, 2020). "One study evaluated 126 patients with HCC and demonstrated that the independent risk factors for prediction of decreased overall survival and disease-free survival post-resection were large tumor size > 5 cm, high preoperative AFP >400 ng/ml, multiple tumors and vascular invasion." (PMID 32426129, 2020). "Successful radiological criteria of downstaging are tumor shrinkage by 30 or 50%, meeting the Milan criteria, meeting the Milan criteria with definition of AFP target levels, meeting the UCSF criteria as well as complete or partial response according to the mRECIST criteria." (PMID 32356179, 2020). "Other independent risk factors for DSS were ECOG performance score (HR 2.72, 95 percent CI 1.35–5.40, P=0.004), AFP level ≥ 400 μg/L (HR 3.16, 95 percent CI 1.02–9.81), tumor size ≥ 10 cm (HR 2.20, 95 percent CI 1.02–4.74), and PVTT status (HR 3.13, 95 percent CI 1.52–6.41, P=0.002)." (PMID 32322268, 2020). "Moreover, we found the predictive performance of STIP1 was stronger than other biomarkers such as AFP, tumor size, and tumor number." (PMID 32426271, 2020). "Moreover, the tumor reduction ratio and rate of AFP change were also similar between the two patient groups (P = 0.8849 and P = 0.7743)." (PMID 32055698, 2020). "Median maximum tumor diameter was 30 mm (10–40 mm) and alpha-fetoprotein was 25 (1.1–2100) IU/mL." (PMID 33050084, 2020). "More evidence has revealed that HCC accompanied with high AFP concentrations have a distinct tumor biology and could be regarded as a subtype of the disease." (PMID 32350243, 2020). "In addition, relevance of tumor markers other than AFP, particularly protein induced by vitamin K antagonist-II, was not evaluable because of incomplete data." (PMID 32487089, 2020). "In the same study, among patients with low AFP levels, increased IL-6 or IL-10 levels were significantly associated with the presence of HCC suggesting that these cytokines may be used as a tumor marker for patients with low AFP." (PMID 32284794, 2020). "The main testicular serum tumor markers include AFP, β-HCG, and LDH." (PMID 33767975, 2020). "In the analyses, tumor size, AFP, and tumor number significantly predicted OS (P < 0.1)." (PMID 32850345, 2020). "However, to more rigorously evaluate potential “on-target, off-tumor” toxicity for AFP TCRs, we examined the ability of AFP TCR engineered T cells to react with a range of primary cells, especially those from essential human organs." (PMID 32425926, 2020). "The growth of the tumor volume was significantly faster in the AFP group compared to the controls." (PMID 32774373, 2020). "In fact, AFP sensitivity drops to 25% if the tumor is smaller than 3 cm in diameter." (PMID 32284794, 2020). "Our results disclosed higher AFP mRNA expression in HCC than non-tumor tissue samples." (PMID 31973032, 2020). "Alpha-fetoprotein (AFP) remains the commonly used diagnostic biomarker since promising markers quite often not directly correlate with the tumor burden." (PMID 32699957, 2020). "Clinicopathological analyses revealed that HOXA5 was negatively correlated with tumor size and AFP." (PMID 32373208, 2020). "Finally, AST, GGT, Child–Pugh class, Cr, AFP, and largest tumor diameter ≥5 cm were selected as significant factors affecting the prognosis for overall survival by the forward selection procedure." (PMID 32149077, 2020).
tumor (continued). "Furthermore, both univariate and multivariate COX regression analyses indicated that P300, like TNM stage, AFP and tumor size, was an independent factor affecting the survival of HCC patients (P = 0.043)." (PMID 32144235, 2020). "In addition, patients with younger age, preoperational AFP level less than 200 ng/mL, normal post-operational AFP or tumor size less than 3 cm were showing a numerically but insignificantly better survival." (PMID 31977318, 2020). "Interestingly, DCP performance is also superior to the one of AFP for HCC tumors with a diameter under 5 cm indicating a possible limitations since its reliability appears to greatly depend on tumor stage." (PMID 32443747, 2020). "Levels of HCC tumour markers, including AFP, CA199, CEA, and CA125, were determined." (PMID 33312206, 2020). "Based on the 8th Union for International Cancer Control classification of HCC, the tumor was graded as T4N0M0 and stage III B. The following tumor markers were detected: alpha fetoprotein (3.8 ng/mL) and protein induced by vitamin K absence/agonist-II (PIVKA-II) (145,000 mAU/mL)." (PMID 31970661, 2020). "Addition of CIN increases detection sensitivity to 52.9% (tumor size less than 3 cm), 85.7% (tumor size between 3 and 5 cm), and 88.5% (4C, tumor size greater than 5 cm), which is higher than for AFP alone (Fisher test, P = .04, <0.01, and < 0.01, respectively)." (PMID 32458568, 2020). "In the univariate analysis, the clinicopathological characteristics including AFP (P = .038), tumour number (P < .001), BCLC stage (P < .001), vascular invasion (P = .003) and ITGBL1 expression (P = .014) were significantly associated with the OS in HCC patients." (PMID 32537856, 2020). "Several recent studies have demonstrated that formate is a useful biomarker in HCC; however, what we have shown is that formate itself is a highly specific and selective biomarker for the prediction of VI and a combination of formate, tumor size and AFP further improves its performance." (PMID 32493393, 2020). "Liver damage and a certain tumour can significantly increase AFP concentrations." (PMID 33090723, 2020). "Furthermore, unfavorable prognostic factors, such as MVI and AFP, were commonly correlated with tumor size." (PMID 32850396, 2020). "Only AFP expression in tumor tissue correlated with its serum levels." (PMID 31897235, 2020). "A multiplex electrochemiluminescence immunoassay has been developed for the simultaneous determination of two different tumour biomarkers (alpha-fetoprotein (AFP) and CEA) in human serum and saliva, using multicolour QD labels and graphene as a conducting bridge." (PMID 33276535, 2020). "This could be related to the larger maximum tumor size and higher AFP level, which indicated a higher tumor load leading to poor prognosis." (PMID 33425729, 2020). "Interestingly, abnormal glycan structures have been recognized as biomarkers in cancer diagnosis, such as tumor-associated glycans CA19–9 and AFP for cancer screening." (PMID 32620165, 2020). "Except for 2 patients who could not undergo lumbar punctures, all children underwent examinations of serum and CSF tumor markers, including AFP and β-HCG." (PMID 32153511, 2020). "Therefore, these AFP constructs were tested as part of a phase I/II trial (NCT00093548) in two HCC patients who had an AFP-expressing tumor and previous treatment for HCC." (PMID 33020428, 2020). "Decreased abundance of AFP in the mouse serum of TC4-bearing mice after cisplatin treatment (4 mg/kg) can therefore not be explained by loss of AFP expression in the tumour." (PMID 33144587, 2020). "Since the 1970s, AFP has been recognized as a tumour marker for the diagnosis of HCC." (PMID 33090723, 2020). "The clinical factors (including age, sex, tumor site, tumor volume, AFP level) were collected." (PMID 33330062, 2020).